TLR2 (toll like receptor 2)
Diseases named in the same sentence as TLR2 in open-access papers (continued):
Sharing a sentence is not in itself a finding about the gene and the disease.
bacterial infection (continued). "In this study, we show that GBS HylB mediates immune suppression and promotes bacterial infection during pregnancy that requires TLR2, TLR4, and IL-10." (PMID 37747229, 2023). "As reported in other bacterial diseases, blocking of TLR2 by bacterial components or TLR2 mRNA degradation by micro RNA need to be clarified." (PMID 38014008, 2023). "Nevertheless, studies on other bacterial infections demonstrated the downregulation of TLR2 gene via different types of mechanisms." (PMID 38014008, 2023). "Among TLRs, TLR2 plays a vital role in the early innate immune response to bacterial infection by initiating the release of pro-inflammatory cytokines and influencing the downstream immune response." (PMID 36838365, 2023). "TLR2 has an alert sentinel function and is the main recruitment/phagocytic receptor for innate cells in case of bacterial infection, and it is also involved in promoting angiogenesis during wound healing." (PMID 35459112, 2022). "They found that bacterial infection induced a reduction in TLR expression (TLR2 and 4) that was restored after BUD and FLU treatment in COPD patients and smokers without COPD." (PMID 35897707, 2022). "During bacterial infections, TLR2 can be stimulated, leading to formation of platelet/neutrophil aggregates, which enhances adhesion of the aggregates to sites of injury or infection." (PMID 35406684, 2022). "An increased expression of Tlr2 has been shown to improve mucus homeostasis and to prompt mechanisms of immune response to protect the host against bacterial infection." (PMID 36052065, 2022). "Vital NETosis is induced by bacterial infections, particularly those due to S. aureus, through the interaction with Toll-like Receptor 2 (TLR2) and Complement Receptors." (PMID 34261496, 2021). "For instance, HSF1 is known to initiate host defense against bacterial infection, partly through promoting early TLR2 signaling activation." (PMID 34944618, 2021). "Our results indicate that exposure to 5-HT in all tested bacterial infections upregulates TLR-2 and pro-inflammatory cytokines expression and protein level in a concentration dependent manner." (PMID 34799637, 2021). "TLR2 is up-regulated in bacterial infections, as its agonists are microbial cell wall components, and its stimulation activates innate immune response cascades to eliminate pathogens." (PMID 34502403, 2021). "TLR1 forms heterodimers with TLR2 and is activated in response to bacterial infections, during embryonic brain development or in neuropathogenesis." (PMID 35010941, 2021). "TLR2 recognizes pneumococcal peptidoglycan and induces an inflammatory response, thus promoting host defense against bacterial infection." (PMID 32753046, 2020). "In order to determine the effect of bacterial infection on TLR2/TLR4 expressions on macrophages, we infected PMA-activated THP-1 with MAP for 24 h." (PMID 33212859, 2020). "If bacterial infection with S. epidermidis, S. aureus or P. acnes would have activated an immune reaction, much higher TLR2 expression would have been expected in the capsules." (PMID 30937475, 2019). "For instance, lincRNA-Cox2 regulates the release of inflammatory mediators and cytokines by stimulation of TLR2 in bacterial infections, and miR-155 exerts an antiproliferative effect on CD8+ T cells in response to the type I interferon signaling." (PMID 31304055, 2019). "Total mRNA was isolated from the prASCs in passage 2 cultured in standard medium to determine the constitutive expression of the relevant receptors for the bacterial infections (TLR-2 for LTA and TLR-4 for LPS)." (PMID 31671899, 2019). "In bacterial infection, the recognition of TLR2 enhances NADPH oxidase-mediated reactive oxygen species (ROS) generation to induce bactericidal activity and inflammatory signal transduction." (PMID 31620121, 2019).
bacterial infection (continued). "It is demonstrated that L. rhamnosus promotes TLR2/Akt activation in response to bacterial infection, thus protecting cells by maintaining the epithelial barrier and promoting intestinal epithelial cell activation against an enterotoxigenic Escherichia coli." (PMID 31480681, 2019). "TLR2 is involved in detecting bacterial infection and in chronic inflammation and is located at the cell membrane, where it recognises and binds to signal molecules." (PMID 31611734, 2019). "The consensus from the previous studies provides solid evidence to support the findings from the present study that TLR2 plays a key role in the immune response against long standing bacterial infections, especially gram +ve predominant lesions." (PMID 30631444, 2018). "We therefore attempted to examine the influence of bacterial infection on TLR2-mediated intracellular signal transduction pathways in naive and BLP-tolerised macrophages." (PMID 28079153, 2017). "The contribution of TLR2 to pulmonary host defense against bacterial infection also appears to be pathogen‐specific." (PMID 29142002, 2017). "Immunoblotting also showed that TLR2 deficiency inhibited LC3 conversion and Lyn phosphorylation upon bacterial infection." (PMID 26735693, 2016). "Recent findings indicate a parallel pathway by which responses to both viral and bacterial infections is controlled via the secretion of soluble TLR2 (sTLR2)." (PMID 27531999, 2016). "We concluded that DEFB131 induces cytokine and chemokine upregulation through the TLR2/NF-κB signaling pathway in RWPE-1 cells during bacterial infection and promotes an innate immune response." (PMID 26649771, 2015). "Upon bacterial infection, splenic neutrophils and Ly6G+ CD11b+ myeloid cells from burn mice had significantly reduced TLR2, TLR4 and TLR5 expression compared to uninfected burn and infected sham mice." (PMID 24454904, 2014). "For example, MyD88 adaptor-like (Mal) acts to bridge MyD88 to TLR4 or TLR2 complex and is capable of mediating NF-kB activation in response to bacterial infection." (PMID 24278275, 2013). "This suggests that, in cases of bacterial infection in asthmatic airways, where mast cells and basophils may be stimulated by both TLR2/4 ligands and by IgE-dependent mechanisms, it is unlikely that IgE-dependent responses are potentiated by pathogen-associated TLR2/4 ligands." (PMID 22470546, 2012). "Recent studies from our group suggested that EGFR is at least in part activated by NTHi via NTHi-derived EGF-like growth factor and plays an important role in negatively regulating TLR2 induction during bacterial infections." (PMID 22132240, 2011). "Airway epithelial cell cultures were utilized to reveal the contribution of TLR2 signaling including NF-κB to SPLUNC1 production upon bacterial infection and TLR2 agonist stimulation." (PMID 21054862, 2010). "Our study thus provides novel insights into the regulation of TLR2 expression in mixed bacterial infections." (PMID 18664270, 2008). "Furthermore, bacterial infections have been shown to exacerbate AD by inducing pro-inflammatory responses through Toll-like receptor 2 (TLR2), leading to the upregulation of the high-affinity IgE receptor (FcεRI) on dendritic cells in AD patients." (PMID 40364168, 2025). "Different than TLR2 and NOD2, IFN-γ is a cytokine responsible for a wide array of immune functions, primarily related to activation of type 1 immunity, which is associated with cell-mediated defense against viral and bacterial infections." (PMID 41369133, 2025). "Existing literature suggests that TLR1 and TLR2 could play a significant role in the immune defense against bacterial infections." (PMID 39949364, 2025). "Tlr2 and Tlr4 play essential roles in signal transduction in bacterial infection." (PMID 38711507, 2024). "Indeed, stimulation with TLR2/4 agonists, which mimicked bacterial infection, increased the m6A level in DDX5-overexpressing cells but decreased it in DDX5 knockdown cells." (PMID 38182816, 2024).
bacterial infection (continued). "Given the prominent role of TLR2/4 in recognizing bacterial PAMPs and activating inflammation through the NF-κB pathway, the TLR2/4 agonists LPS, FSL-1, and Pam3CSK4 were used to explore the mechanism through which DDX5 activated the TLR2/4/NF-κB pathway upon bacterial infection." (PMID 38182816, 2024). "We found that bacterial infection induced extracellular release of CsCKM-1/2, and recombinant CsCKM-1/2 stimulated the activity of peripheral blood leukocytes (PBLs) and exerted antimicrobial effects in a manner that required Toll-like receptor 2 (TLR2)." (PMID 36936949, 2023). "The evidence supporting the role of mast cells in fighting bacterial infections is based on the finding that transfer of wild-type mast cells (TLR2+/+) reduced the pathogen load and myeloid cell recruitment in TLR2-deficient (TLR2−/−) mice infected with Mycobacterium tuberculosis." (PMID 37663654, 2023). "In the mouse S. pneumoniae meningitis model, the bacterial infection caused the alteration of BBB permeability in both wild-type and TLR2 deficient mice and the higher Evans blue concentration in the brains of TLR2 deficient mice, compared with the control mice." (PMID 36769171, 2023). "Furthermore, studies have suggested that HSF1 is required to initiate the host defense against bacterial infection through early activation of TLR2 signaling." (PMID 37893128, 2023). "TLR2/NF-κB pathway plays an important role in bacterial infectious diseases." (PMID 35222679, 2022). "Next to the LPS-recognizing TLR4, TLR2 is also important in bacterial infections." (PMID 35406684, 2022). "Similarly, the expression levels of four typical immunological factors, namely, P38, P65, JNK1 and TLR2, each of which represents an immune-related pathway, all increased after bacterial infection." (PMID 34093564, 2021). "Thus, G-CSF plays a key role in regulating granulopoiesis during bacterial infection, and TLR2 and TLR4 are essential to the host defense mechanism." (PMID 33763386, 2021). "TLR2 enhanced chemokine expression in the primary immune cell, such as PBMCs component macrophages and DC precursors, representing a systemic defense against bacterial infection." (PMID 32280674, 2020). "This further confirms that the identified miRNAs are upregulated by leptospiral LPS through the TLR2 immune axis, and these miRNAs can be significant signature molecules to differentiate leptospiral infection from other bacterial infections with which it is often confused." (PMID 32669469, 2020). "The differences seen in TLR2 expression between both cohorts could therefore also be influenced by the change in monocyte subpopulations following more frequent bacterial infections in DS." (PMID 31611734, 2019). "In contrast, during a high-level stimulation, as would occur following bacterial infection, TLR2 might also participate in damaging inflammatory responses." (PMID 29904087, 2018). "In line with our results, TLR2 upregulation on monocytes during the clinical course of infections has already been observed in adults and seemed even to be a possible predictor of recurrence in patients with bacterial infectious diseases." (PMID 30131804, 2018). "However, it is unclear the impact of bacterial infection on TLR2-mediated signal transduction pathways in BLP-tolerised macrophages." (PMID 28079153, 2017). "In response to TLR2 or 4 ligation, as might be observed during secondary bacterial infection, cytokine secretion was markedly decreased in BVDV2-infected MDMΦ, compared to non-infected MDMΦ." (PMID 27420479, 2016). "Taken together, we characterize TLR2 and Lyn as new regulators of bacteria-induced autophagy and phagocytosis both in vitro and in vivo, providing new insight into the molecular mechanism of immune responses against acute bacterial infection." (PMID 26735693, 2016).
bacterial infection (continued). "Platelet transcripts were affected similarly by each bacterial infection, which suggests that each stimuli was activating through common pathways, most likely the TLR2-NFКB pathway, in the platelet precursor cell, the megakaryocyte, which we previously published on." (PMID 26148065, 2015). "TLR2 specifically is involved in detection of Gram-positive surface markers (including lactobacilli) while the complement receptors are important for phagocytosis and inflammatory cascades in response to bacterial infections." (PMID 25127240, 2014). "We hypothesize that, as in UDD bacterial infections are more frequent, lymphocytes expressing TLR2 and TLR4 are already mobilized and ready to mount the immune-response." (PMID 25133198, 2014). "BPs also blocks LPS-induced up-regulation of TLR2 in macrophages, demonstrating that BPs may affect a large spectrum of bacterial infection." (PMID 24167596, 2013). "However, there are few studies demonstrating the effect of TLR2 on CD36 expression upon bacterial infection." (PMID 24058538, 2013). "However, TLR2 expression is greatly increased during bacterial infections through an NF-κB-dependent mechanism." (PMID 18423053, 2008). "Thus, regulation of TLR2 expression is likely an important immune-regulatory mechanism, commonly involved in host defence against bacterial infections." (PMID 18423053, 2008). "Indeed, previous literature shows that genetic polymorphisms in innate immune signaling factors, such as IL-6, TLR2 and IL-1β may explain the variation in disease severity during bacterial infections in preterm and term newborns." (PMID 38562936, 2024). "However, whether the same DDX5/METTL3-mediated m6A machinery also regulates TLR2/4/NF-κB-mediated inflammatory responses during bacterial infection was unclear." (PMID 38182816, 2024). "It has been demonstrated that the TLR2 pathway regulates Ca2+ mobilization through the cell; TLR2 agonist, Pam3Cys, stimulates Ca2+ influx in neutrophils, human mast cells, and airway epithelial cells via TLR2-dependent signaling and modulates proinflammatory response to bacterial infection." (PMID 35281105, 2022). "Likewise, tlr genes are often up-regulated when fish deal with a bacterial infection, but there is now evidence that spirulina feed significantly enhanced the immune response of gibel carp (Carassius auratus gibelio) through the Tlr2 pathway." (PMID 34675821, 2021). "To evaluate whether invasive potential differences between all the tested bacteria to cause varied stimulation effects on proinflammatory response, we further compared the expression level of TLR-2, Il-1β, and iNOS mRNAs during bacterial infection the MG-63 cells." (PMID 28800779, 2017). "However, only TLR2 knockdown showed impaired LC3 puncta formation upon bacterial infection." (PMID 26735693, 2016). "Furthermore, S100B quantification in patients suffering from severe bacterial infections involving TLR2 activation might be relevant." (PMID 27047454, 2016). "The expression of TRLs in the urothelial cells plays a key role in immune response against UTIs, with TLR2, TLR4, and TLR5 considered to be most important in bacterial infections." (PMID 41596750, 2026). "Studies examining the impact of bacterial infections on sperm quality have utilized TLR agonists, such as Pam3Cys (a TLR2 agonist) and lipopolysaccharide (LPS, a TLR4 agonist) in experimental settings." (PMID 40242391, 2025). "TLR2 and TLR4 play a key role in the development of an inflammation in responseto a bacterial infection." (PMID 40264577, 2025). "This suggests that berberine and carvacrol treatment inhibited the mRNA expression of TLR2 and TLR4 in bacterial infections." (PMID 40431224, 2025). "TLR2 and TLR4 are the most critical PRRs during bacterial infection and function to promote inflammatory responses upon invasion of bacteria." (PMID 38182816, 2024).
bacterial infection (continued). "Previous studies have shown that the stimulation of the Toll-like receptor-2 (TLR-2) signaling pathway leads to the MyD88-dependent NF-κB p50/p65 activation in immune cells and other cell types in response to bacterial infections." (PMID 39081324, 2024). "TLR-2 and TLR-4 are the two major TLRs that recognize PAMPs during bacterial infections and have been extensively studied and evaluated in A. baumannii infection." (PMID 39149030, 2024). "Activation of TLR2/4 can induce NF-κB-regulated inflammatory cytokines, such as interleukin 6 (IL-6) and tumor necrosis factor-alpha (TNF-α) during bacterial infection." (PMID 38182816, 2024). "Bacterial infection, or stimulation with PAM, induced a significant signal in the reporter cells, confirming the inducible interaction between TLR2 and VCL." (PMID 37023213, 2023). "Taken together, our results show that bacterial infection, or PAM stimulation, induces TLR2 interaction with VCL through specific residues of the TIR domain outside the BB loop." (PMID 37023213, 2023). "TIRAP, also known as MYD88 adapter-like (Mal), is an important link between MYD88 and the receptor complex formed by TLR2 and TLR4 activation following bacterial infection." (PMID 35140801, 2022). "Previous studies have documented TLRs, particularly TLR2 and TLR4 play a crucial role in regulating the intensity of the immune-inflammatory response during bacterial infection." (PMID 35413908, 2022). "TLR2- and TLR9-independent mechanisms promote osteoclastogenesis in RANKL-primed precursors during intracellular bacterial infection." (PMID 36226943, 2022). "It is well established that Toll-like receptors (TLRs), particularly surface TLRs such as TLR2, TLR4, and TLR5, play an essential role in defending against this bacterial infection." (PMID 36194127, 2022). "Additional functional studies are warranted to obtain a better understanding of the interaction between LECT2 and TLR2 and to clarify the roles of LECT2 in the regulation of the immune response to bacterial infection in teleosts." (PMID 34093564, 2021). "Therefore, again, the human data correlate with the mouse model; collectively, the data suggest that downregulation of TLR2 and/or TLR4 as a result of heme released by traumatic injuries may be an important cause of increased clinical susceptibility to bacterial infection." (PMID 34520397, 2021). "One mechanism reported for certain BRMs, for example, is to act like TLR agonists, particularly TLR-2 and TLR-4 in bacterial infections, helping enhance the response to microbial infections." (PMID 34696778, 2021). "TLR2, 4, and 9 are the principal TLR involved in the pathogenesis of bacterial infections which are activated in microglia during the early phase of bacterial CNS infection." (PMID 29880000, 2018). "Especially important for bacterial infections are TLR2, TLR4 and TLR9: TLR2 is activated by bacterial lipopeptides, TLR4 recognizes endotoxin (LPS) and pneumolysin (an important pathogenic factor of S. pneumoniae), and TLR9 is activated by bacterial DNA." (PMID 25528768, 2014). "Given that M. avium is a TLR2 agonist and that Camp mRNA expression upon bacterial infection depends on TLR2 activation, our data suggest that TNF production after TLR2 stimulation by M. avium is crucial to induce murine cathelicidin expression." (PMID 25400920, 2014). "The endometrial epithelial and stromal cell responses to lipopeptides via TLR2, TLR1, and TLR6 provide a mechanism linking a wide range of bacterial infections to inflammation of the endometrium." (PMID 24437488, 2014). "TLR2 and CARD15 play a role in the initiation of inflammatory and immune responses to bacterial infections." (PMID 18005441, 2007). "TLR2 and TLR4 receptors are defense mechanism receptors of the body against bacterial infection." (PMID 40431224, 2025).